RASA1 (RAS p21 protein activator 1)
Diseases named in the same sentence as RASA1 in open-access papers (continued):
Sharing a sentence is not in itself a finding about the gene and the disease.
vascular malformation (12 papers, 2020 to 2025). A non-neoplastic disorder that is the result of defects of vascular morphogenesis. "First, those presenting with > 1 vascular malformation were likely to harbor an underlying genetic condition such as HHT or RASA1." (PMID 38506930, 2024). "Vascular malformations are linked to mutations in RAS p21 protein activator 1 (Rasa1 or p120RasGAP)." (PMID 36551964, 2022). "In early studies, RASA1 appeared to be essential for embryonic blood vessel development; subsequently, a germline mutation in RASA1 was associated with vascular malformations." (PMID 33096593, 2020). "And recurrently mutated genes were identified in several vascular malformations as well including TEK/TIE2 mainly in venous malformations, GNA11/14 mainly in vascular tumors, KRAS/NRAS/RASA1/HRAS mainly in AVMs, GNAQ, IDH1/2, AKT1, PTEN and PIK3CA." (PMID 34736485, 2021). "Genetic analyses of ACVRL1, ENG, and SMAD4 (in addition to EPHB4 and RASA1) are considered reasonable in all cases of high-flow intracerebral vascular malformations regardless of other HHT signs." (PMID 40259928, 2025). "First, we performed manual analysis and variant calling of the sequencing data for the genes known to cause HHT (ACVRL1, ENG, GDF2, SMAD4) or vascular malformation syndromes with similar phenotypes (EPHB4, RASA1), as well as PIK3CA, which has been shown to modify vascular malformation phenotypes." (PMID 39062925, 2024).
hereditary hemorrhagic telangiectasia (10 papers, 2015 to 2025). A disorder of angiogenesis leading to arteriovenous dilatations: cutaneo-mucosal hemorrhagic telangiectasias and visceral shunting. "The first refers to pathologies such as hereditary hemorrhagic telangiectasia (HHT) and RASA1 gene mutations." (PMID 35893282, 2022). "Later, other studies reported the presence of RASA1 mutation in atypical CMs as well as cases with aneurysmal malformation of the vein of Galen (VOGM) and Hereditary hemorrhagic telangiectasia (HHT)." (PMID 36293054, 2022). "Other genetic variants described as frequently linked with cerebral arteriovenous fistulas and VGAMs include RASA1 variants, associated with Capillary Malformation—Arteriovenous Malformation 1 (CM-AVM 1) or with Rendu-Osler-Weber disease (Hereditary Hemorrhagic Telangiectasia or HHT)." (PMID 35547535, 2022). "The most frequently associated genetic mutations involve the hereditary hemorrhagic telangiectasia (HHT) genes (ENG, ACVRL and SMAD4) and RASA1 -- which are also implicated in brain AVM and VOGM, respectively." (PMID 38506930, 2024). "These include hereditary hemorrhagic telangiectasia (HHT) and capillary malformation-arteriovenous malformation (CM-AVM) which have been attributed to inherited mutations in RASA1, endoglin, and activin receptor-like kinase 1 (ALK1)." (PMID 36198763, 2022). "According to the ISSVA classification, AVM can manifest as sporadic lesions, in patients with Hereditary hemorrhagic telangiectasia (HHT) and in patients with capillary AVM (CAVM) that are associated with Ras GTPase-activating protein 1 (RASA-1) mutation." (PMID 34541367, 2021).
RASopathies (10 papers, 2014 to 2023). "The fourth RASopathy variant was a c.2446_2447delGA variant in RASA1 predicted to cause LOF, which was inherited maternally, though no maternal phenotype was documented by the treating physician." (PMID 36959127, 2023). "Phosphorylation of the RASopathy proteins RAF1, PTPN11, and BRAF is altered in NS and NSML due to mutations in their corresponding genes, whereas RASA1 altered phosphorylation is associated to mutant SHP2 models and not to its own mutation." (PMID 34229750, 2021). "We find enrichment in RASopathy mutations for NF1, while RASA1 and SHOC2 have mainly cancer mutations." (PMID 24803665, 2014). "Upon suspicion of an RASopathy during the clinical follow up, trio WES analysis was performed, revealing the previously unreported heterozygous variant NM_002890.3:c.693-5A>G in the RASA1 gene." (PMID 36980822, 2023). "Interestingly, one patient showed a RASopathy profile with NF1 truncation and mutations in RASopathy genes like RASA1 and RASA2, which is known from cutaneous melanoma." (PMID 31500314, 2019). "In addition, we verified by exomeanalysis that the patient did not have any pathogenic variants in the genes associatedwith Noonan Syndrome and other rasopathies (PTPN11,SHOC2, KRAS, CBL,SOS1, RAF1, HRAS,NRAS, RASA1, SPRED1,BRAF, MAP2K1, MAP2K2, RIT1 andRRAS)." (PMID 27561113, 2016). "In this context, ERAS adds up to the list of genes whose mutation can lead to overgrowth syndromes (as AKT, PIK3CA, PTEN) or RASopathies (as H-RAS, RASA1, NF1 and RAF1, among others)." (PMID 34771750, 2021).
hepatocellular carcinoma (8 papers, 2015 to 2025). A malignant tumor that arises from hepatocytes. "RASA1 mutations have been documented in hepatocellular carcinoma, breast cancer, and melanoma." (PMID 33096593, 2020). "For instance, recent studies have identified miRNA binding site polymorphisms in genes implicated in migration, invasion, and angiogenesis, such as RASA1, COL1A2, CA9, CD147, VHL, and RYR3, which can influence susceptibility to hepatocellular carcinoma (HCC)." (PMID 41409896, 2025). "The hypoxia-inducible miR-182 was reported to target two different RasGAPs: RASA1 in hepatocellular cancer and oral cavity squamous cells carcinoma, and DAB2IP in colorectal carcinoma." (PMID 33096593, 2020). "In hepatocellular carcinoma, it has also been found that down-regulation of RASA1 promotes angiogenesis under hypoxic conditions." (PMID 31857500, 2019). "Using the top three as examples: RASA1 was shown to be involved in the development of some sarcomas, CDK signaling was found to be a potential therapeutic target in hepatocellular carcinoma, and S100A4 was shown to maintain cancer-initiating cells in head and neck cancers." (PMID 37200395, 2023).
colon carcinoma (7 papers, 2012 to 2023). "Some researchers have demonstrated that miR-188-5p promotes oxaliplatin resistance by targeting RASA1 in colon cancer cells." (PMID 37402449, 2023). "RASA1 expression is significantly reduced in KRAS wild-type colon cancer cells, indicating that miR-21 activates the RAS signaling pathway by downregulating RASA1 expression." (PMID 37516822, 2023). "In another study, RASA1 expression was shown to be regulated by the oncogene miR-21, promoting invasion and tumor formation ability in colon cancer RKO cells." (PMID 32612205, 2020). "RASA1 protein levels in RKO cells are much lower than in the other five colon cancer cell lines, indicating that miR-21 activated RAS signaling pathways by down-regulating RASA1 expression." (PMID 35627101, 2022).
Chylothorax (6 papers, 2019 to 2023). The presence of chyle in the thoracic cavity. "Inherited inactivating mutations in EPHB4 and RASA1 are also responsible for the development of lymphatic vascular abnormalities in humans, including lymphedema, chylous ascites and chylothorax, lymphatic-related hydrops fetalis, central conducting lymphatic anomaly, and abnormal lymphatic flow." (PMID 35015735, 2022). "Patients with a mutation in RASA1 are at a higher risk of developing Parkes–Weber syndrome, which presents itself as a disease with upper and lower extremity lymphedema with some cases of chylothorax and/or chylous ascites." (PMID 31083300, 2019). "The deletion of RASA1, a Ras GTPase-activating protein that negatively regulates lymphatic vessel growth, resulted in a lymphatic vessel disorder characterized by extensive lymphatic vessel hyperplasia, dilation, leakage, and early lethality caused by chylothorax." (PMID 31083300, 2019). "Although this explained the lymphatic hyperplasia observed in Rasa1-deficient mice, it failed to explain the appearance of chylothorax." (PMID 32824219, 2020).
lung carcinoma (6 papers, 2014 to 2023). "It's worth mentioning that 14 patients had RASA1 mutations among 938 tested lung cancer patients (1.5%) in this study; RASA1 gene was detected only by the panel of 520 cancer‐related genes." (PMID 35702826, 2023). "For example, miR-182 was reported to suppress lung tumorigenesis and lung cancer cell proliferation through downregulation of RGS17 or RASA1." (PMID 26338969, 2015). "However, there were 5 cases of RASA1 mutations among 59 NF1 mutation patients (8.5%), which indicated that the occurrence of RASA1 mutations is obviously related to the occurrence of NF1 mutations in lung cancer patients." (PMID 35702826, 2023). "We found that RASA1 enforced expression reduced cell proliferation and increased the response to cisplatin in KRAS mutant lung cancer cells." (PMID 29440633, 2018). "This microRNA is capable of promoting lung cancer by subexpressing several regulators (SPRED1, SPRED2, SPRY1, RASA1, SPRY3 and SPRY4) in RAS / MAPK signaling, which leads to an increase in the signaling of this pathway." (PMID 29053755, 2017).
lymphedema (6 papers, 2017 to 2025). Excess fluid collection in tissues, causing swelling. "RASA1 mutations are associated with lymphedema in a subset of carriers." (PMID 29125824, 2017).
non-small cell lung carcinoma (6 papers, 2015 to 2025). A group of at least three distinct histological types of lung cancer, including non-small cell squamous cell carcinoma, adenocarcinoma, and large cell carcinoma. "In non-small cell lung cancer, RASA1 has also been found to be associated with tumor progression and mediated MEK inhibition." (PMID 31857500, 2019). "In non-small cell lung cancer (NSCLC), NF1 co-mutation with RASA1 has been described." (PMID 40361412, 2025). "Mutations in RASA1 and NF1 co-occur in human non-small cell lung cancer, which may reflect independent mechanisms by which RASA1 and NF1 inhibit RAS or the clonal diversity within these tumors that preferentially selects one of these mechanisms." (PMID 33435458, 2021).
ovarian carcinoma (6 papers, 2020 to 2022). A malignant neoplasm originating from the surface ovarian epithelium. "Regarding MAPK signaling regulators, it was shown that circ-ITCH is downregulated in ovarian cancer and exerts its onco-suppressive role through the miR-145-5p/RASA1 axis; RASA1 is an inhibitor of MAPK signaling." (PMID 34205978, 2021). "The circ-ITCH can act as competing endogenous RNA (ceRNA) to sponge miR-145 and enhance RASA1 expression and inhibit malignant progression of ovarian cancer." (PMID 33096593, 2020). "circEPSTI1 regulated ovarian cancer progression by sponging miR-942.CircITCHsuppressed ovarian carcinoma by sponging miR-145 to regulating RASA1 signaling." (PMID 32640974, 2020). "For instance, low expression of circ-ITCH combined with increased expression of the RASA1-targeting miR-145 predicts poor prognosis in ovarian cancer." (PMID 33096593, 2020). "Taken together, circ-ITCH impeded cell proliferation, invasion and glycolysis by regulating the miR-106a/CDH1 axis, which was in agreement with previous reports that circ-ITCH retarded ovarian carcinoma progress by targeting the miR-145/RASA1 axis." (PMID 32714095, 2020).
basal cell carcinoma (4 papers, 2016 to 2024). A carcinoma involving the basal cells. "Alterations in the binding sites of either RASA1 or RAS p21 proteins are associated with basal cell carcinomas." (PMID 38874808, 2024). "RASA1 helps in control of cellular proliferation and its mutation is associated with basal cell carcinoma." (PMID 27829003, 2016). "Mutations within ACVRL1 and MADH4 may be associated with pulmonary hypertension, while basal cell carcinoma was described in RASA1 mutations." (PMID 33807613, 2021).
Capillary malformation - arteriovenous malformation (4 papers, 2013 to 2023). "Capillary malformation-arteriovenous malformation (CM-AVM) syndrome is an autosomal dominant disorder due to germline heterozygous mutations in the RASA1 gene." (PMID 35209959, 2022). "Pathogenic variants in RASA1 are typically associated with a clinical condition called “capillary malformation-arteriovenous malformation” (CM-AVM) syndrome, an autosomal dominant genetic disease characterized by a broad phenotypic variability, even within families." (PMID 36980822, 2023). "Whether the hyperactive Ras signaling caused by inactivating RASA1 mutations in Capillary Malformation-Arteriovenous Malformation (CM-AVM) functions through an endothelial cell-autonomous manner is still unknown." (PMID 23663822, 2013).
liver cancer (3 papers, 2016 to 2025). An epithelial or non-epithelial malignant neoplasm that arises from the liver. "RASA1 encodes RAS P21 protein activator 1, whose levels are associated with liver cancer cells, and which regulates cell migration and angiogenesis." (PMID 41409896, 2025). "The expression of RASA1 can be down-regulated by miRNA, which promotes cell proliferation and inhibits liver cancer cell apoptosis." (PMID 37446885, 2023).
melanoma (3 papers, 2016). A malignant, usually aggressive tumor composed of atypical, neoplastic melanocytes. "Here, we have shown that RASA1 is inactivated by mutation or, more frequently, by decreased expression in melanoma and that RASA1 suppresses anchorage-independent growth in vitro and tumor growth in vivo." (PMID 26993606, 2016). "Large scale melanoma genomic studies listed in cBioPortal have shown somatic missense mutations of RASA1 in 2 out of 121 patients (P135S and E510K), 1 of 91 (R245H), and 3 of 228 (P130L, K468N, S509N, and R913Q)." (PMID 26993606, 2016). "In our study, loss of RASA1 triggered activation of R-Ras and Ral-A and R-Ras was required to drive colony formation driven by RASA1 inactivation in melanoma cells with BRAF mutation." (PMID 26993606, 2016). "In this study, we focused on RASA1, which featured two novel, clustered somatic missense mutations (Y472H and L481F) and sought to determine the function of RASA1 in melanoma tumorigenesis." (PMID 26993606, 2016). "Through gain of function and loss of function studies, we have shown that RASA1 plays a tumor suppressive role in melanoma." (PMID 26993606, 2016). "To understand molecular mechanisms underlying RASA1 function, we first examined whether RASA1 modulates Ras activity in melanoma cells." (PMID 26993606, 2016). "Therefore, at least in part, RasGAP activity of RASA1 underlies its tumor suppressive function in melanoma." (PMID 26993606, 2016). "Therefore, our study suggests that RASA1 inactivation and subsequent R-Ras activation is one of the possible mechanisms leading to Ral-A activation in melanomas with BRAF mutation." (PMID 26993606, 2016). "In addition to mutations, loss of RASA1 expression was frequently observed in metastatic melanoma samples on melanoma tissue microarray (TMA) and a low level of RASA1 mRNA expression was associated with decreased overall survival in melanoma patients with BRAF mutations." (PMID 26993606, 2016). "Our study supports that RASA1 suppresses melanoma growth at least in part by regulating R-Ras activity in melanoma cells harboring oncogenic BRAF mutations." (PMID 26993606, 2016). "In order to address RASA1 function in melanoma, we first evaluated RASA1 protein levels in human melanoma cell lines." (PMID 26993606, 2016). "In order to identify Ras isoforms that are regulated by RASA1 in melanoma, GTP-bound active Ras was probed with isoform specific antibodies against H-, K-, N-, M-, and R-Ras." (PMID 26993606, 2016). "First, we examined the effect of RNAi-mediated suppression of RASA1 function in melanoma cell lines on anchorage-independent soft agar colony formation." (PMID 26993606, 2016). "In our extension screening involving an additional 97 melanoma samples from 96 patients, a frame shift deletion in RASA1 was observed affecting P135." (PMID 26993606, 2016). "When RASA1 was expressed in UACC257 and WM983C melanoma cells with low endogenous RASA1 expression, decreased soft agar colony formation was observed compared to controls with empty vector, consistent with a tumor suppressive role for RASA1." (PMID 26993606, 2016). "RASA1 levels were over 50% down-regulated in 12 out of 21 (57%) human melanoma cells compared to a normal human epithelial melanocyte line (NHEM)." (PMID 26993606, 2016). "Further study is required to determine the role of RASA1 in melanomas with oncogenic NRAS mutations, especially in metastasis, and the effect of RASA1 on R-Ras activation in melanomas that are wild-type for BRAF and NRAS." (PMID 26993606, 2016). "Utilizing a melanoma whole genome sequencing (WGS) data from 13 patients, we identified two novel, clustered somatic missense mutations (Y472H and L481F) in RASA1 (RAS p21 protein activator 1, also called p120RasGAP)." (PMID 26993606, 2016). "R-Ras activation and subsequent Ral-A activation via inactivation of RASA1 may provide an additional mechanism driving melanoma formation." (PMID 26993606, 2016).